MPO (myeloperoxidase)
Diseases named in the same sentence as MPO in open-access papers (continued):
Sharing a sentence is not in itself a finding about the gene and the disease.
tumor (continued). "In summary, the authors identified a specific microbiota-derived metabolite and MPO present during chemotherapy treatment that led to the accumulation of ROS and directly stopped the proliferation of tumour cells." (PMID 38874485, 2024). "Loss of host myeloperoxidase and pharmacological inhibition of myeloperoxidase in combination with immune checkpoint therapy significantly delayed tumor growth." (PMID 38367056, 2024). "Infiltration of CD11b+ and MPO+ cells was negligible in all treatment groups compared to the tumor-free control prostate tissue." (PMID 38689823, 2024). "Our previous studies indicated that neutrophils trigger tumor cell ferroptotic death through intercellular transfer of MPO-containing granular contents into tumor cells and that MPO activity is essential for the neutrophil cytotoxicity." (PMID 38806658, 2024). "Elevated levels of MPO are used as markers for inflammatory diseases, and in some cancers, are believed to aid in tumour progression." (PMID 38398138, 2024). "Following engulfment, neutrophils undergo fragmentation via a lysosome-mediated process and subsequently induce tumor cell death by releasing their contents, such as MPO." (PMID 38806658, 2024). "MPO+ neutrophils and CD68+IDO1+ tumor-associated macrophages (TAMs) were enriched in the epithelial compartment, and myeloid lineage cells were located nearest to tumor cells." (PMID 38951801, 2024). "On the one hand, MPO is involved in promoting tumor initiation, development, and migration; on the other hand, MPO enhances innate immune action during tumor elimination." (PMID 38275657, 2024). "In Eμ-Myc tumours, the overall immune composition was altered relative to healthy lymph nodes, with an increase in neutrophils (defined as CD11b + MPO+), and a decrease in Tregs, dendritic cells, and CD8 + T cells." (PMID 38311785, 2024). "The presence of KPCY6419 tumors increased total number of isolated neutrophils and MDSC in the spleen of both WT and MPO−/− mice compared to WT healthy (tumor-free) mice." (PMID 38367056, 2024). "Using intravital imaging with skinfold window chamber murine models, we evaluated changes in the MPO activity and ROS levels within the tumor microenvironment during KPCY6419 tumor growth in real-time." (PMID 38367056, 2024). "MPO exhibits significant interactions with infiltrating immune cells in MM, such as neutrophils, suggesting its potential role in modulating tumour immunity." (PMID 38923838, 2024). "The immunohistochemical detection of MPO-positive neutrophilic granulocytes revealed a limited number of inflammatory cells in the tumor tissue of all groups following ECT treatment." (PMID 39075095, 2024). "The components of NETs, such as myeloperoxidase (MPO) and histones, can eliminate tumors and inhibit tumor progression and metastasis." (PMID 38697992, 2024). "These non-tumor bearing mice displayed infrequent prostatic inflammatory infiltrates with F4/80, CD11b, and MPO positive staining of less than 2% each." (PMID 38689823, 2024). "This accumulation inhibits CD4+ and CD8+ T cells, primarily through the expression of myeloperoxidase (MPO) and Fas/FasL, thereby promoting tumor growth." (PMID 38474175, 2024). "The enrichment of NETs in target organs is positively correlated with tumor metastasis, and serum NETs DNA, which is usually measured by MPO-DNA, has also become a potential biomarker for predicting cancer metastasis." (PMID 39529085, 2024). "The nitrosonium ion, an oxidative product of NO catalyzed by MPO, reduces caspase-3 activity via the nitroxylation of the caspase-3 thiol group, protecting tumor cells from apoptosis." (PMID 38275657, 2024). "Tumor‐associated neutrophils exhibit plasticity, adopting either an antitumorigenic N1 (MPO+ CD206−) or a pro‐tumorigenic N2 (MPO+ CD206+) phenotype." (PMID 39718130, 2024). "Exenatide treatment led to decreased infiltration of NETs in tumor, and decreased peripheral MPO-DNA." (PMID 39300084, 2024).
tumor (continued). "NET ingredients, such as MPO, NE, and histones, can eliminate tumors and inhibit tumor progression and metastasis." (PMID 38697992, 2024). "The immunohistochemical detection of MPO-positive neutrophilic granulocytes revealed a similar number of inflammatory cells in the tumor tissue following ECT treatment in the three groups." (PMID 39075095, 2024). "Our data demonstrated significant delay in tumor growth using an MPO specific inhibitor, verdiperstat, combined with ICT compared to ICT or inhibitor alone." (PMID 38367056, 2024). "These mobilized neutrophils convey myeloperoxidase (MPO) to tumor cells either directly or through close cell-to-cell interaction, instigating lipid peroxidation within tumor cells and fostering tumor cell ferroptosis." (PMID 38965216, 2024). "Host MPO deficiency significantly reduced both CD11b+Ly6G+ myeloid cells, macrophages (CD11b+F4/80+) and exhausted CD4+PD1+CTLA4+ T cells within the tumor microenvironment." (PMID 38367056, 2024). "F4/80 detection in each group displayed greater density compared to CD11b and MPO, which were both primarily located at the tumor margin." (PMID 38689823, 2024). "CXCL1 causes the recruitment of neutrophils into the tumor niche; these cells express myeloperoxidase (MPO) and Fas ligand (FasL), which inhibits the anti-tumor effect of lymphocytes." (PMID 38673949, 2024). "NET components such as myeloperoxidases (MPO), proteinases, and histones demonstrate the ability to eliminate tumors, inhibit tumor growth, and hinder metastasis." (PMID 38474175, 2024). "To investigate clinical significance of TANs infiltration in LN metastasis of BCa, we performed immunohistochemistry staining for CD66b or MPO‐specific markers for neutrophils‐in the tumor tissues of 207 patients with BCa." (PMID 36670069, 2023). "In some cancers, MPO enhances tumor progression and metastases resulting in a higher migration of tumor cells." (PMID 37776707, 2023). "Recent studies from our laboratory showed that tumour-bearing MPO knock-out mice (MPO KO) had reduced tumour growth when compared to their wild-type (WT) littermates." (PMID 37627581, 2023). "In the irradiated environment, MPO shifted to the anti-tumor role, lowering the viability of glioma cells and diminishing their proliferation." (PMID 37833255, 2023). "MPO has been found to contribute to tumour initiation by creating a hypermutagenic environment through the oxidation and modification of DNA by MPO-derived oxidants." (PMID 37627581, 2023). "By immunofluorescence observation of NETs protein markers citH3 and MPO, we found that NETs infiltrate the tumor site widely." (PMID 37958984, 2023). "Mechanically, neutrophil myeloperoxidase (MPO) was required for tumor growth inhibition mediated by 3-IAA and FOLFIRINOX." (PMID 37291097, 2023). "MPO is a kind of enzyme secreted by activated neutrophils and as an important component of NETs,which plays a crucial role in the tumor immune microenvironment." (PMID 37935721, 2023). "By detecting MPO‐DNA, NE‐DNA, and H3Cit with enzyme‐linked immunosorbent assay (ELISA) in serum and plasma, NET was correlated with poor tumor staging, poor prognosis, and high risk of metastasis." (PMID 38018346, 2023). "Collectively, these data support a role for MPO in facilitating immune suppression by inhibiting anti‐tumour T‐cell responses." (PMID 37699574, 2023). "The pharmacological inhibition of the myeloperoxidase pathway in PMN-MDSCs restored DC cross-presentation, suggesting that drugs targeting the myeloperoxidase pathway have the potential to restore DC cross-presentation and enhance anti-tumor immune responses." (PMID 37830618, 2023). "In an oxygen-deficient environment, neutrophils are able to transfer granules containing myeloperoxidase into tumor cells, thereby inducing the accumulation of lipid peroxides and iron in tumor cells and triggering ferroptosis." (PMID 37600785, 2023).
tumor (continued). "Given that MPO is increased in the MM BM microenvironment in vivo and promotes MM PC proliferation and inhibits T‐cell function in vitro, the potential of specifically inhibiting MPO to limit MM tumour development in vivo was examined." (PMID 37699574, 2023). "Further analyses revealed that the enhanced leukocyte infiltrate of ITGB4 KD tumor nodules was characterized by arginase-1- and myeloperoxidase-positive cells." (PMID 36932441, 2023). "On the one hand, protein components in NETs, such as MPO, histones and proteases, can play an anti-tumor role and kill tumor cells, thereby inhibiting tumor growth and development." (PMID 37373412, 2023). "Inhibiting enzymatic activity in a lung tumour engraftment model resulted in reduced tumour growth when compared to mice with active MPO." (PMID 37627581, 2023). "Correspondingly, the gene encoding myeloperoxidase (MPO), an enzyme highly expressed in human Neut, showed significantly elevated tumor expression in CMS4." (PMID 36911097, 2023). "In summary, our study has described, for the first time, that myeloid‐derived MPO contributes to MM disease progression and identifies MPO as a viable therapeutic target to reduce tumour progression in vivo." (PMID 37699574, 2023). "In mice, CD11b+Ly6G+Ly6Clow G‐MDSCs acquire higher arginase and MPO activity, as well as increased ROS production in tumor‐bearing mice compared to CD11b+Ly6G+Ly6Clow neutrophils from naive tumor‐free mice, which mediates tumor immunosuppression." (PMID 36326214, 2023). "The present study also demonstrated that LPS injection after general anaesthetic exposure induced tumour volume reduction, high MPO and CCR2 expression, more neutrophil infiltration, and less M1 and pan macrophage infiltration." (PMID 35953652, 2023). "MPO has been proposed as a tumor marker in hematologic malignancies and has been demonstrated to be elevated at baseline prior to treatment with anthracyclines." (PMID 37106424, 2023). "Specifically, elevated levels of localised MPO activity within the BM supports MM PC homing and MM tumour growth." (PMID 37699574, 2023). "In the frozen sections, the MPO (green fluorescence) and citH3 (red fluorescence) were full of disordered tumor tissues, and their fluorescence intensities were higher than those of normal tissues adjacent to tumors." (PMID 37153547, 2023). "Components such as myeloperoxidase (MPO), histones and proteases in NETs can directly kill tumours and inhibit tumour growth and metastasis." (PMID 37980632, 2023). "Azide, cyanide, or the addition of catalases inhibit MPO activity and prevent neutrophil-mediated tumor cell lysis thereby indicating therapeutic approaches." (PMID 37376417, 2023). "Despite higher expression of Cxcl2, we saw no increase in tumour neutrophil recruitment (determined by percentage of Myeloperoxidase‐positive cells) when DKK1 was overexpressed in Nicd/Akt or KrasG12D/gTrp53 tumours." (PMID 35924447, 2023). "To gain insight into the tumour architecture, we compared spatial interactions between major immune lineages across MPO categories." (PMID 36725935, 2023). "Mechanistically, MPO induced the expression of key MM growth factors, resulting in tumour cell proliferation and suppressed cytotoxic T‐cell activity." (PMID 37699574, 2023). "Perioperative continuous intravenous infusion of Lido and Dex significantly reduced the production of NETs (MPO and H3Cit) and the expression of tumor metastasis biomarkers (VEGF-α, MMP-3, and MMP-9) in the peripheral blood of NSCLC patients." (PMID 36910600, 2023). "The observed effect of MPO on tumour growth was most likely due to its augmenting pro-tumourigenic collagen production, angiogenesis and interaction with the surrounding microenvironment." (PMID 37513924, 2023). "Irradiation resulted in a significant increase in tumor-infiltrating neutrophils and inflammatory Ly6Chigh monocytes/macrophages and a 10-fold increase in MPO activity in the TME." (PMID 37833255, 2023).
tumor (continued). "NETs can be involved in the adaptive immunity activation by priming T cells or exert direct cytotoxicity on tumor cells through some of its components, such as MPO." (PMID 36983067, 2023). "In our previous results published, MPO expression was significantly higher in post- treatment than in pre-treatment tumor samples." (PMID 37762335, 2023). "While MPO has both pro- and anti-tumour properties, most of the evidence suggests that it supports tumour initiation and progression." (PMID 37627581, 2023). "We found that metastatic tumour cells (cytokeratin 19+) in both chemotherapy-treated patient cohorts were surrounded by higher numbers of neutrophils (MPO+) compared with the untreated patient cohort." (PMID 35022267, 2022). "Authors in that work concluded that the observed impact of MPO on tumor growth was due to its interaction with surrounding fibroblasts to promote collagen release and remodeling of the ECM." (PMID 36293108, 2022). "NETs are neutrophil-derived webs of DNA decorated with granular proteins, including NE, matrix metalloproteinase 9, MPO, and cathepsin G, with the ability to promote tumor cell proliferation, angiogenesis, and metastasis." (PMID 35036439, 2022). "Our previous studies have shown that MDSC-produced MPO can mediate homocitrullination in the tumor microenvironment making homocitrullinated epitopes good targets for tumor therapy." (PMID 35464453, 2022). "The mechanism for ferroptotic killing of tumor cells by neutrophils involved intercellular transfer of myeloperoxidase encased in granules to the tumor cells." (PMID 35065965, 2022). "A recent study investigating the myeloperoxidase (MPO) and histone expression using immunohistochemistry showed NETs in the tumor tissue of patients with OSCC." (PMID 35784290, 2022). "Activated neutrophils express factors, such as elastase and myeloperoxidase (MPO), that stimulate specific receptors in tumor cells and activate tumor growth-related signaling pathways to facilitate tumor progression." (PMID 35787261, 2022). "More importantly, using in situ triple color immunofluorescence, we observed the co-expression of PD-L1 with CD66b and MPO on tumor-infiltrating neutrophils in UCB tissues." (PMID 35386697, 2022). "Since these results suggest that neutrophils participate in the effect of ICI, we evaluated the impact of the combination of α-PD-L1/α-PD-1 with α-MPO on tumor growth in both LLC models." (PMID 35269405, 2022). "These MPO+ neutrophils have been reported to contribute to the tumor progression, through the support of angiogenesis." (PMID 35158807, 2022). "We also showed that probes ICAM1, calreticulin, PD-L1, neuropilin-1, galectin-3 and MPO were spatially associated with immunogenic cell death and, together with the enriched standard cell types, they might serve as an early predictive biomarker of induced anti-tumor immunity in situ." (PMID 35788566, 2022). "It cannot be ignored that the enzymes produced and released by neutrophils, such as myeloperoxidase, neutrophil elastase, and matrix metalloproteinases, can also promote tumor progression." (PMID 36686802, 2022). "Surprisingly, the MPO levels were a more effective indicator of the response to tumor treatment compared with the TnI (SMD = 2.46, 90% CI −0.26–5.19, I2: 96%) and NT-proBNP levels (SMD = 1.08, 90% CI −0.82–2.98, I2: 96%)." (PMID 36551214, 2022). "Another study has revealed that the increased secretion of CRCSC-exos was accompanied by elevated tumor infiltration of myeloperoxidase neutrophils, which promotes tumorigenesis of CRC cells via IL-1β." (PMID 35461336, 2022). "Tumor-associated-neutrophils can influence macrophage polarization to tumor-associated-macrophages (TAM) by secreting Il-8, TNF-α and MPO." (PMID 35163180, 2022). "This occurs by an endocytic process in which the tumor material ends up in phago-lysosomes containing granule-derived material such as MPO and lactoferrin." (PMID 35884427, 2022).
tumor (continued). "After cancer cell identification, neutrophils then need to have physical contact with the tumor cells in order to release cytotoxic mediators such as myeloperoxidase (MPO), H2O2, reactive oxygen species (ROS), and proteases." (PMID 35784290, 2022). "MPO expression levels in 480 tumor tissues were markedly higher than those in 41 normal tissues (P = 0.001)." (PMID 35912260, 2022). "The scores for each cell type in the tumor microenvironment showed the following ratios: CD3+:CD20+:CD138+:CD56+:CD68+:MPO = 0.44: 0.13: 0.09: 0.09: 0.22: 0.03." (PMID 34636027, 2022). "Parallel changes were further demonstrated in the immunohistochemical detection of NET-associated citrullinated histone H3, neutrophil elastase, Protein Arginine Deiminase 4 (PAD4) and MPO in resected tumor tissues." (PMID 36012397, 2022). "Ultrasound-guided biopsy revealed diffuse infiltration of undifferentiated tumor cells and immunohistochemistry (IHC) indicated that the tumor was positive for myeloperoxidase (MPO), cluster of differentiation (CD) 34, CD43, CD68, CD117, and Ki67." (PMID 34579724, 2021). "Similar results were obtained when we measured the level of NETs in tumor homogenate using the MPO-DNA complex." (PMID 34771497, 2021). "IL-17 was found to potentiate the anti-tumor activity of neutrophils by enhancing the production of cytotoxic molecules, including ROS, MPO, TRAIL and IFNγ." (PMID 34572138, 2021). "The enhanced production of ROS together with arginine depletion, nitric oxide radicals, MPO, and inhibitory cytokines contribute to the immunosuppressive features of G-MDSCs; however, at the same time, these molecules have anti-tumor activities." (PMID 34572138, 2021). "To understand the properties of the microbiota found in this study, we analyzed the correlation by taking previously reported results (DAI score, ELISA levels of MPO and IL-1β, and tumor number) from the same set of experiments." (PMID 34249773, 2021). "Tumor infiltration by MPO expressing neutrophils was shown to be an independent prognostic biomarker with a favorable prognosis in human breast cancer." (PMID 35003081, 2021). "In tumor-bearing mice, GrMDSCs exhibit lower levels of phagocytosis but higher levels of activation or production of arginase-1, myeloperoxidase (MPO) and ROS that suppress T cell function." (PMID 34359674, 2021). "Collectively, neutrophil-induced NETs act as an inhibitor for development of tumor metastasis through elastase, MPO, and other enzymes." (PMID 34660642, 2021). "Pharmacological inhibition of MPO in combination with checkpoint blockade reduced tumor progression in different tumor models." (PMID 35003065, 2021). "Our results showed that this elevated MPO activity after D-mannose treatment suppressed tumor growth." (PMID 34944979, 2021). "MPO-positive neutrophils were detected throughout the tumour section and there was a significant increase in neutrophil infiltration compared to the control biopsies." (PMID 34203378, 2021). "IHC for F4/80, CD163, and MPO was performed and a significant increase in MPO+neutrophils was found in primary tumours upon Dox+Zol treatment compared to any other treatment." (PMID 34290237, 2021). "Excessive ROS and RNS production together with elevated MPO activity result in the suppression of anti-tumor T and NK cells and can lead to local tissue injury." (PMID 34572138, 2021). "Normalized NF-κB activation per unit tumor mass demonstrated an increase in NF-κB transcriptional activation within B16F10 tumors grown in MPO−/− animals compared to MPO+/+ animals, which had been previously macroscopically demonstrated." (PMID 33652682, 2021).